STAT3 (signal transducer and activator of transcription 3)
Diseases named in the same sentence as STAT3 in open-access papers (continued):
Sharing a sentence is not in itself a finding about the gene and the disease.
tumor (continued). "The IL-6/JAK/STAT3 signaling pathway drives the metastasis, proliferation, survival, and invasiveness of tumor cells in the tumor microenvironment by suppressing the antitumor immune response." (PMID 37176567, 2023). "Continuously activated STAT3 in tumor cells as a pivotal oncogenic mediator and an effective transcription factor has been extensively studied." (PMID 36714534, 2023). "Further, in tumor cells, STAT3 inhibition counteracted tumor growth and tumor resistance towards various therapeutic approaches." (PMID 38069260, 2023). "In tumor cells, PD-L1 can rely on signal transducer and activator of transcription 3 (STAT3) signaling pathway to accumulate in the cytoplasm." (PMID 37275876, 2023). "Resveratrol (3,5,4′-trihydroxystilbene, Res), a polyphenolic compound found in red grapes and several other plants, was reported to inhibit tumor growth and improve drug chemosensitivity by targeting the STAT3 signaling pathway." (PMID 37298405, 2023). "In GBM cells (U373MG cells), these EVs reduced mRNA expression levels indicative of tumor progression, proliferation, migration, and epithelial–mesenchymal transition (STAT3, c-Myc, Mcl-1, ITG-β1, Vimentin, and Slug)." (PMID 37240536, 2023). "(L) STAT3 immunohistochemical staining for the tumor samples derived from HePG2 cells expressing control shRNA or STAT3 shRNA." (PMID 36656267, 2023). "The JAK2/STAT3 cascade plays a key role in many cellular processes, including growth, division, programmed cell death, immunological escape and resistance, and tumor angiogenesis." (PMID 36740668, 2023). "Similar findings were observed in GBM; RBPJ can increase GBM cell proliferation, invasion, stemness, and tumor initiating ability by enhancing the activation of the IL‐6/STAT3 pathway." (PMID 37576862, 2023). "IL-6 is a pleiotropic cytokine that is highly produced in tumor-bearing hosts and inhibits the antigen presentation ability of DCs by activating signal transducer and activator of transcription 3 (STAT3)." (PMID 37965271, 2023). "Herein, we provide in vitro and in vivo evidence that HNC018 exhibits anti-tumor effects by suppressing the c-MET/STAT3/AKT signaling axis." (PMID 37373393, 2023). "Another study showed that heat shock protein 72 present on tumor-derived EVs mediates immunosuppressive functions of MDSCs through STAT3 activation." (PMID 37834100, 2023). "IL-23 influences tumor cells via T-cell responses by positively affecting the STAT3 activity in tumor growth, elevating TH17 activity and regulatory T cells (Tregs)." (PMID 37176567, 2023). "Systemic delivery of VEGFR-2 and PLXDC1 siRNA to tumor endothelium reduced tumor burden, and STAT3 siRNA directed to bone marrow endothelium in a model of bone metastasis prolonged survival in tumor-bearing mice." (PMID 36735106, 2023). "YFSJ and its component quercetin can inhibit the overactivation of skeletal muscle mitophagy mediated by the abnormal activation of the Stat3/HIF-1α/BNIP3 signaling pathway induced by the tumor inflammatory microenvironment, thereby alleviating CRF." (PMID 36814560, 2023). "This study demonstrated that crocin has anti-tumor activity through inhibiting IL-6/STAT3 signaling pathway." (PMID 37404473, 2023). "By inhibiting the encoding of E-cadherin and increasing the nuclear transcription of signal transducer and activator of Transcription 3 (STAT3), Dimer PKM2 can lead to a loss of EMT in tumour cells and promote tumour cell invasion and migration." (PMID 37108242, 2023). "In CLL cells, the constitutive activation of STAT-3 and NF-κB causes the delivery of IL-6, which further increases JAK2/STAT3 stimulation, leading to the IL-6/JAK/STAT3 feed-forward loop that controls tumor proliferation." (PMID 37048814, 2023).
tumor (continued). "Our study provides inspiration for the development of tumor therapy by suppressing the migratory behavior of TNBC cells through the regulation of STAT3 signaling." (PMID 37651362, 2023). "IL-6 is an important member of the cytokine network that mainly transmits signals through the STAT3 signaling pathway in cancer, thereby promoting tumor invasion and metastasis." (PMID 37981718, 2023). "In the tumor microenvironment, continuous stimulation with IL-6 can activate JAK2, resulting in STAT3 phosphorylation and thereby promoting tumor growth, drug resistance, and metastasis." (PMID 37817809, 2023). "For example, the activation of STAT3 signals maintains the self-renewal and tumourigenic potential of glioblastoma stem cell-like tumour cells (GSC)." (PMID 37368660, 2023). "IHC results showed that the combination decreased the expression of Ki67, CDK2, and p-STAT3 expression in tumor tissues, while Pal alone showed elevated CDK2 expression and upregulated p-STAT3 expression." (PMID 37752122, 2023). "Bioluminescence imaging revealed that tumor growth was significantly lower in both STAT3- and SRF-knockdown groups than in the control." (PMID 37558923, 2023). "Due to its important role in tumor development, STAT3 has been investigated as a potential therapeutic target for new drugs, and the results are promising." (PMID 37371647, 2023). "Reduced GSDMD expression speeds up tumor proliferation and S/G2 transition of cells by stimulating the STAT3 and PI3K/PKB pathways." (PMID 37752941, 2023). "Immunofluorescence staining of pSTAT3 confirmed the increase in STAT3 activation in tumor cells (αSMA−/CD45−) from KPC-HAPLN1 tumor-bearing mice." (PMID 37095087, 2023). "CYTL1 has been reported to inhibit STAT3 phosphorylation, and a decrease in STAT3 phosphorylation expression was accompanied by an increase in anti-angiogenic effects, thereby inhibiting tumor progression." (PMID 36899891, 2023). "The results showed that STAT3 induced the promoter activity of CCL2 in tumor cells transfected with the promoter region of CCL2." (PMID 38008713, 2023). "The combined treatment, by inhibiting STAT3 functions, can negatively impact the STAT3-dependent induction of PD-L1, reducing immune escape and tumor growth." (PMID 36672229, 2023). "Hyperactivation of STAT3 leads to a series of tumor promoting events, such as immunosuppression in tumor-infiltrating cells, dampening antigen presentation, and inhibition of tumor-killing activities." (PMID 36986550, 2023). "In the present study, the responsiveness of proliferating and docetaxel (DTX)-induced senescent cancer cells to small molecule STAT3 inhibitor Stattic and its analogues was evaluated using tumour cell lines." (PMID 36825563, 2023). "We previously revealed that TAMs support tumor progression through STAT3 activation in several malignant tumors." (PMID 36961655, 2023). "MiR-103a decreases PTEN levels in tumor microenvironment monocytes by increasing the polarization of M2 macrophages, which in turn promotes the activation of AKT and STAT3, leading to the development of tumor immunosuppression." (PMID 37371458, 2023). "In lieu of depleting Breg cells, inhibitors of MEK, BTK, and STAT3 have been reported to hinder Breg formation and promote anti-tumor immunity across various mouse tumor models." (PMID 37868967, 2023). "In both in vivo and in vitro experimental settings, AL was shown to be beneficial in lowering tumor angiogenesis and development by blocking STAT3 activation in CRC cells." (PMID 37894369, 2023). "Experimental and animal studies indicate that STAT3 inhibition prevents tumor growth and metastasis." (PMID 37308913, 2023). "Targeting constitutively activated STAT3 in tumors has been demonstrated to directly induce tumor cell death and inhibit growth in vivo." (PMID 37630387, 2023).
tumor (continued). "STAT3 plays a vital role in the interaction between tumor cells and GAMs, and its activation significantly enhances tumor-promoting immune regulation while inhibiting tumor-killing immune response." (PMID 36969167, 2023). "This suggested that GBM-derived STAT3 is transferred to the macrophages inducing their phenotypic shift towards a tumor-supportive phenotype." (PMID 37240536, 2023). "By suppressing the STAT3 pathway, immunosuppression of the tumor microenvironment was also achieved." (PMID 37765192, 2023). "Of note, IL-6 promotes the survival and proliferation of tumor cells and attenuates the antitumor ability of tumor-infiltrating immune cells through the IL-6/JAK/STAT3 signaling pathway in the TME." (PMID 38455086, 2023). "This discrepancy can perhaps be explained by the fact that STAT3 has heterogeneous functions and although it is frequently described as an oncogene, its opposite role as a tumor expressor most likely depends on the expression of its various gene isoforms." (PMID 36980682, 2023). "Il-6 via the membrane receptor activates non-receptor tyrosine kinases including JAK2, which induce the JAK2/STAT3 cascade for angiogenesis and tumor enlargement because of regulating progression of the cell cycle." (PMID 37373969, 2023). "Recent studies have shown that inhibition of STAT3 can reduce the expression of PD-L1, thereby inhibiting tumor inflammatory response and improving the immune response to tumor cells." (PMID 38116545, 2023). "It was also shown that the WW domain-containing oxidoreductase inhibits tumor growth and metastasis in TNBC by inhibiting JAK2 phosphorylation and impeding the association of JAK2 with STAT3, thereby preventing STAT3 phosphorylation." (PMID 37237509, 2023). "We carried out a co-immunoprecipitation (CoIP) assay in tumor cells using the antibody against STAT3 or NLK." (PMID 38008713, 2023). "Some tumours showed an early activation of potential bypass‐pathways as through increased phosphorylation of AKT or STAT3." (PMID 37604687, 2023). "STAT3 is a meeting point for a number of oncogenic pathways and is constitutively activated in both tumor cells and tumor-infiltrating immune cells." (PMID 37496997, 2023). "Consistent with the in vitro cell experiments, we observed that PTP 9 and anti-PD-1 cotreatment induced a significant increase in tumor expression of Cxcl11, Ccl5, Stat1, Stat3, Tap1, Irf1, Casp8, and Pdl1, compared with anti-PD-1 treatment alone." (PMID 36968224, 2023). "STAT3 is involved in the proliferation of tumor cells, inhibition of apoptosis and promotion of stemness and chemotherapy resistance in cancer cells." (PMID 38098005, 2023). "TCGA data indicated that STAT3 levels in PDAC were higher than in tumor-adjacent tissue, which was related to the poor prognosis of PDAC patients." (PMID 37743465, 2023). "RMS-high group was related to worse prognosis, which was partly attributed to significant activation of EMT, Notch, IL-2/STAT5, IL-6/JAK/STAT3, angiogenesis signaling pathways, which was instrumental in tumor invasion." (PMID 37124622, 2023). "The JAK/STAT3 activation pathway is thought to be crucial for a number of oncogenic activities, including tumour growth, differentiation, angiogenesis, and survival." (PMID 36768291, 2023). "Treatment using PARP inhibitors (PARPi) results in acquired PARPi-resistance, promoted by STAT3 activity both in tumor cells and in immune and CAF cells." (PMID 38248100, 2023). "In contrast, a broad range of human cancers are manifested by sustained activation of STAT3, as evidenced by high p-STAT3 levels in tumor tissues, which predicts poor prognosis in general." (PMID 37893115, 2023). "In vitro xenograft tumor assays confirmed that STK24 can positively administer STAT3/VEGFA signaling pathway." (PMID 36720310, 2023).
tumor (continued). "Tumor cells’ intrinsic genetic events lead to the activation of certain transcription factors, e.g., nuclear factor-κB (NF-κB), signal transducer and activator of transcription 3 (STAT3), and hypoxia-inducible factor 1α (HIF1α)." (PMID 36260158, 2023). "STAT3 pathway activation in NSCLC induces tumor resistance towards conventional and small molecule targeted therapy." (PMID 36986550, 2023). "TfR1 down-regulation activates the JAK/STAT3 pathway, promotes the tumor cells transformation from G1 to S phase, and enhances cells motility and infiltration." (PMID 36910614, 2023). "Our data suggest that modulation of GCSF signaling in tumor-bearing mice diminishes aberrant STAT3-induced development and activation of immunosuppressive myeloid cells and boosts the frequency of immune-stimulatory cells such as cDC1s and CD11c+/MHCII+ MFs." (PMID 36911097, 2023). "In triple‐negative breast cancer (TNBC), the autocrine loop formed by the VEGF/VEGFR2 axis involving STAT3, Myc, and Sox2 contributes to the enhancement of the tumor stem cell‐like phenotype." (PMID 38077251, 2023). "Their role as positive tumor regulators has been associated with B cells that express “signal transducer and activator of transcription 3” (STAT3), that contributes to a proangiogenic environment thus promoting tumor growth." (PMID 36776840, 2023). "A-FABP released from adipose tissue promotes tumor stemness by activating the IL-6/STAT3/ALDH1 pathway." (PMID 36880535, 2023). "The role of STAT3 in OvCa has been extensively studied with a significant body of evidence demonstrating the importance of STAT3 in tumor development, survival mechanisms, metastasis, stemness, and chemoresistance." (PMID 37173951, 2023). "IL-6, as a tumor promoting cytokine, triggers the Janus kinase (JAK) associated with the receptor, stimulating STAT3 phosphorylation and activation." (PMID 37035153, 2023). "In particular, RAF1 expression correlated with the expression of STAT3 targets involved in the control of angiogenesis, a crucial process necessary for tumor growth and metastasis development." (PMID 37020037, 2023). "In this study, we identify TMEM25 as an EGFR binding protein to prevent monomeric EGFR-mediated phosphorylation of STAT3 in the basal state, therefore functioning as a tumor suppressor to inhibit TNBC progression." (PMID 37095176, 2023). "Indoleamine-2,3-dioxygenase 1 (IDO1) and signal transducer and activator of transcription 3 (STAT3) have emerged as significant targets in the tumor microenvironment for cancer therapy." (PMID 37630387, 2023). "Under the stimulation of carcinogenic signals, STAT3 is continuously activated to remain in the nucleus in an activated state, continuously activating target genes, and promoting the growth of tumor cells." (PMID 38111074, 2023). "Signal transducer and activator of transcription 3 (STAT3) is a transcription factor (TF) with multiple tumor-promoting effects in NSCLC, including proliferation, anti-apoptosis, angiogenesis, invasion, metastasis, immunosuppression, and drug resistance." (PMID 36672335, 2023). "Concerning CRC, persistent STAT3 activation has been linked to enhanced CRC cell proliferation and tumor growth and is correlated with poor prognosis of clinical outcomes for CRC patients." (PMID 37760971, 2023). "Stroma cells produce miR-214 upon tumor cell signals which involve the activation of the IL-6/STAT3 signaling." (PMID 36639824, 2023). "They found that KRASG12D protein induces fatty acid oxidation in a STAT3-dependent manner, driving and polarizing macrophages into a pro-tumor TAM similar to M2." (PMID 36845720, 2023). "Tumour tissue from patients treated with neo-adjuvant endocrine therapy (<4 months) also displayed increased Stat3 and Src signalling." (PMID 36266450, 2023). "Tumor-bearing mice treated with pSi-STAT3/liposomes formed fewer metastases and smaller tumors than the control groups." (PMID 38067351, 2023).
tumor (continued). "These isoforms have been suggested as the reason for the occasionally observed opposing roles of STAT3 in cancer: an oncogene, on one hand, and a tumor suppressor on the other." (PMID 37097001, 2023). "First, aberrant activation of STAT3 in tumor cells plays an important role in the maturation of DCs." (PMID 37724127, 2023). "Further, we demonstrated that KD or inhibition of STAT3 with WP1066 not only suppressed MB tumor growth, but also augmented the sensitivity of MB tumors to cisplatin." (PMID 37190167, 2023). "Another study using C188-9, a small inhibitor of STAT3, showed tumour regression in mice xenografted with radiation-resistant HNSCC lines." (PMID 36980527, 2023). "As an MGMT transcription factor, the activation and nucleation of Tyr705 in STAT3 are critical for DNA damage repair in tumor cells." (PMID 38071213, 2023). "IL-6 acts directly at IL-6R located on tumor cells to induce the expression of STAT3 target genes, and then drive tumor proliferation, survival and drug resistance." (PMID 37404767, 2023). "One of the possible mechanisms of CAFs’ EMT activation in tumor cells and, as a consequence, metastasis, is a STAT3-mediated reduction in E-cadherin expression." (PMID 38003931, 2023). "Mechanically, LC-MS, CoIP, and rescue experiments revealed that GINS2 promoted tumor progression through the STAT3/MYC axis in the OS." (PMID 36873736, 2023). "Tumor cells exposed to IL-6 activate the oncogenic STAT3 transcription factor to promote epithelial-to-mesenchymal transition (EMT), which is the first step for tumor cell migration." (PMID 36891151, 2023). "PI3Kγ plays a crucial role in promoting microglia chemotaxis and IL-11 secretion, which can in turn lead to tumorigenesis and resistance to TMZ by activating the STAT3-MYC axis in tumor cells." (PMID 37598273, 2023). "In melanoma, flubendazole reduced the expression of phosphorylated STAT3 in tumor tissue and the expression of PD-1 expression, while also decreasing MDSC levels in tumors." (PMID 37511453, 2023). "The codelivery of imatinib mesylate and STAT3 siRNA using the layer-by-layer assembly of AuNPs showed a significant reduction in tumor volume, and weight, and suppressed the STAT3 protein expression drastically." (PMID 37765317, 2023). "These tumours have high epithelial signal transducer and activator of transcription 3 (STAT3) activity and develop stiff, matricellular-enriched fibrosis associated with high epithelial tension and short patient survival." (PMID 37046716, 2023). "Consistently, Rh4 reduced the expression levels of HDAC4, IL-6 and p-STAT3 in tumor tissues of nude mice intratumorally injected with LPS as comparison to the LPS group." (PMID 37843550, 2023). "For instance, C188‐9 is a potent STAT3 inhibitor and has been assessed in a clinical phase I study for advanced tumours (NCT03195699)." (PMID 37278400, 2023). "Suppression of SOCS3 in macrophages exerted anti-inflammatory and anti-tumor effects through the hyperactivation of STAT3 in the myeloid cell." (PMID 37025997, 2023). "For example, STAT3 participates in the regulation of SOX4 to promote tumor progression in hepatic cell carcinoma." (PMID 37298609, 2023). "By inhibiting the activation of c-Met/Src/STAT3 signaling axis, it can inhibit the survival, proliferation and angiogenesis of tumor cells." (PMID 36959792, 2023). "To explore differentially expressed tumor intrinsic signaling pathways in advanced PCa, we analyzed STAT3-dependent signaling profile at the proteome level." (PMID 37573301, 2023). "In contrast, IL‐37 hinders tumor growth by promoting the polarization of TAMs from M2 to M1 by blocking IL‐6/STAT3 signaling." (PMID 38098217, 2023).